CAV1 (caveolin 1)
Diseases named in the same sentence as CAV1 in open-access papers (continued):
Sharing a sentence is not in itself a finding about the gene and the disease.
cancer (continued). "The decreased expression of CAV-1 promotes the rapid proliferation of cancer cells." (PMID 33935779, 2021). "Indeed, recent studies implicate intracellular CAV1 in regulating various organelle compartments, with particular emphasis on roles in autophagosomes and cancer." (PMID 33931969, 2021). "On the other hand, Cav-1 was also shown to be involved in cancer cell migration and metastasis." (PMID 33774714, 2021). "In this context, the role of Cav1 in cancer progression raises an intense debate." (PMID 34196606, 2021). "Cav1 triggers, and plays a key role in, all the features described as the hallmarks of cancer." (PMID 34207120, 2021). "It is reported that CAV1 scaffolding domain may be critical in controlling the dynamic phenotype of cancer cells by facilitating the interaction of specific signal transduction pathways." (PMID 34684779, 2021). "As our results also showed a decrease in Cav-1 as well as integrins αv and β3, it is possible that artocarpin may at least in part inhibit cancer cell motility via a Cav-1-dependent downregulation of such integrins." (PMID 33920031, 2021). "Based on the RWE, one could reasonably extrapolate that as a cancer becomes more aggressive there is more stromal metabolism, and as such, less Cav-1 in the surrounding stroma." (PMID 34813586, 2021). "In cancer cells and fibroblasts, oxidative stress stimulates Cav-1 upregulation." (PMID 34572135, 2021). "Finally, understanding how CAV1 participates in EV genesis and function is an exciting new field of CAV1 research that holds considerable promise in the development of cancer therapies." (PMID 32458269, 2020). "However, hypoxia in cancer cells and in the colon of the mouse intestine led to increased Cav1 expression." (PMID 33692993, 2020). "For instance, CAV1 and dynamin-2, which are both important for caveola-mediated endocytosis and caveola assembly, are highly expressed in bladder cancer and possibly contribute to the progression of this type of cancer." (PMID 32458269, 2020). "There was a positive association between CAV1 and ATG4C protein expression in cancer cells (P<0.001, phi coefficient = 0.368); a positive correlation between CAV1 and ATG4C protein expression in stromal cells was also identified (P = 0.002, phi coefficient = 0.345)." (PMID 32401768, 2020). "In addition to cancers, there are many other diseases involving the regulation of Cav‐1 methylation." (PMID 32508059, 2020). "Along these lines, caveolin-1 antagonists or inhibitors could offer an interesting strategy to improve H-1PV efficacy in cancer with elevated levels of caveolin-1." (PMID 33096814, 2020). "Thus, CAV1 appears to participate in molecular mechanisms that control metabolic switching both in the stromal and cancer cell compartments." (PMID 32458269, 2020). "Because CAV-1 over-expression is believed to be a key element in cancer development, we employed real-time reverse transcription PCR (RT-PCR) to explore whether TL affects Cav-1mRNA expression in vitro." (PMID 32733649, 2020). "CAV1 was highly expressed in cancer tissues in gene dataset GSE77199 and gene dataset GSE6344." (PMID 32990143, 2020). "Thus, it is still unclear if altered expression of CAV1 is directly related to cancers or if aberrant signals drive anomalous CAV1 expression in different type of tumors." (PMID 32825330, 2020). "Caveolin-1 also plays an important role in the EMT of cancer biology and tissue fibrosis." (PMID 32926104, 2020). "Understanding the molecular interplay between Cav-1 and metabolic modulation could help uncover druggable metabolic targets or pathways for cancer therapy." (PMID 32528105, 2020). "Indeed, several membrane proteins required for endocytosis become dysfunctional during cancer development, as is the case for CAV1." (PMID 32458269, 2020).
cancer (continued). "Therefore, a variety of components, such as Cortactin, Caveolin-1, Tks4/5, and protein tyrosine kinase Src of invadopodia, are usually used as indicators to gauge the mobility and invasion potentials of cancer cells in vitro and in vivo system." (PMID 32033570, 2020). "CAV1-mediated control of signaling events is relevant in cancer." (PMID 32458269, 2020). "Furthermore, we now know that CAV1 expression alters mitochondrial function in a number of ways, yet the relevance of these mechanisms in cancer is still poorly understood, as is also the case for peroxisomal CAV1." (PMID 32458269, 2020). "This suggests that intracellular CAV1 regulates cancer through alternative signaling outputs." (PMID 32811828, 2020). "However, in situations where PTPN14 expression is relatively low (endogenous expression in cancer cells), E-cadherin expression becomes necessary to promote CAV1 dephosphorylation and thereby preclude CAV1-mediated migration, invasion, and metastasis." (PMID 32152405, 2020). "High expression of CAV1 in cancer cells and stromal cells was 60.0% (57/95) and 50.6% (40/79) respectively, suggesting that CAV1 expression in EOC tissues was significantly reduced when compared with noncancerous ovarian tissues(P = 0.013, P = 0.002, respectively)." (PMID 32401768, 2020). "Interestingly we found that FOXP1 and CAV1, genes that are commonly repressed by HMGA1 in cancer, were positively associated with HMGA1-lnc expression." (PMID 33505435, 2020). "The presence of CAV1 at the plasma membrane is necessary for migration and invasion processes, since disruption of membrane rafts by targeting CAV1 or cholesterol reduces the metastatic potential of cancer cells." (PMID 32458269, 2020). "The DNA methyltransferases play key roles in CAV1 expression in different stages of many cancers." (PMID 32508059, 2020). "Finally, we show that PTPN14 overexpression blocks CAV1-enhanced migration, invasion, and metastasis of cancer cells due to its catalytic activity." (PMID 32152405, 2020). "Caveolin-1 (Cav-1), a main component of caveolae, participates in multiple cellular events such as immune responses, endocytosis, membrane trafficking, cellular signaling and cancer progression." (PMID 31991790, 2020). "Given the ubiquity among cancer cells of Caveolin-1 and the actin cytoskeleton, Macrocybin may constitute a common therapeutic agent for a variety of cancers." (PMID 33353176, 2020). "Additionally, caveolin-1 levels are elevated in metastatic or multidrug-resistant human cancer cell lines." (PMID 32676485, 2020). "On the one hand, the survival is longer in cancer patients with higher Cav-1 protein level." (PMID 31901898, 2020). "Moreover, the behavior of normal and cancer cells with alterations in CAV1-expression is different in MAMs." (PMID 32458269, 2020). "Quite to the contrary, CAV1 promotes metastasis and multi-drug resistance in late stages of cancer." (PMID 32458269, 2020). "An increasing number of studies have evaluated Cav-1 expression in cancer." (PMID 31297035, 2019). "This suggests that inhibitors which block the caveolin-1–p85α interaction could function as new therapies to reduce cancer metastases." (PMID 30650664, 2019). "In this work, delineating from pathway annotation analyses, only upregulated genes were correlating with different types of metabolic processes in primary hepatocytes lacking CAV1, and downregulated genes were related mainly to cancer-associated processes." (PMID 32082178, 2019). "CAV1 is a protein that has been ascribed a dual role in cancer, depending on cancer type and stage." (PMID 31362353, 2019). "Caveolin-1 (CAV1) is a scaffolding protein with a controversial role in cancer." (PMID 31362353, 2019). "In cancer cells, CAV-1 functions as an anti-apoptotic protein that promotes cell survival." (PMID 30981205, 2019). "Cav1 therefore plays complex roles in the regulation of cancer cell metabolism." (PMID 31803361, 2019).
cancer (continued). "However, in subsequent years it became clear that the role of CAV1 in cancer is far more complicated." (PMID 31362353, 2019). "Thus, in cancer cells (HeLa), cav-1 overexpression increased PI3K activity, while in fibroblasts the opposite effects were observed." (PMID 30995923, 2019). "Specifically, our results suggest that microRNA/mRNA interactions miR-27a/Foxo1, miR-27a/Mef2c, miR-27b/Cxcl12, miR-27b/Mef2c, miR-140/Cxcl12, miR-199a/Cav1, and miR-199a/Junb may contribute to muscle wasting in cancer cachexia." (PMID 31013615, 2019). "It is suggested that Cav-1 is a critical molecule in the treatment of anti-cancer drug." (PMID 31759347, 2019). "Thus, AT2R activation reduces migration, invasion, and metastasis of cancer cells by PTP1B-mediated CAV1 dephosphorylation and inhibition of the CAV1/Rab5/Rac-1 pathway." (PMID 31484460, 2019). "We further predicted new microRNA–mRNA interactions, such as miR-27a/Foxo1, miR-27a/Mef2c, miR-27b/Cxcl12, miR-27b/Mef2c, miR-140/Cxcl12, miR-199a/Cav1, and miR-199a/Junb, which may contribute to muscle wasting in cancer cachexia." (PMID 31013615, 2019). "As such, CAV1 may also have some potential in the diagnosis and as a therapeutic target in cancer disease." (PMID 31362353, 2019). "In conclusion, we identified new microRNA–mRNA interactions, such as miR-27a/Foxo1, miR-27a/Mef2c, miR-27b/Cxcl12, miR-27b/Mef2c, miR-140/Cxcl12, miR-199a/Cav1, and miR-199a/Junb, that may contribute to muscle wasting in cancer cachexia." (PMID 31013615, 2019). "Upregulation of CAV-1 has been reported to contribute to multiple drug resistance in cancer cells." (PMID 30981205, 2019). "Caveolin-1 (Cav-1) plays an important role in the development of various human cancers." (PMID 31297035, 2019). "In addition, there is evidence that CAV1 is implicated in several aspects of EMT, thus driving cancer progression." (PMID 31362353, 2019). "We observed caveolin-1 localized to the rear of fast-moving cancer cells in 3D matrix." (PMID 31607653, 2019). "Notably, the GAG-modified version of CA9 (PG-CA9) showed an impaired internalization in cancer cells due to translocation of PG-CA9 to caveolin-1 enriched membrane regions." (PMID 30767150, 2019). "Moreover, TGF-β triggers in fibroblasts increased oxidative stress, autophagy/mitophagy, aerobic glycolysis, and downregulation of caveolin-1 (Cav-1): these alterations can extend to surrounding fibroblasts and support cancer cell growth." (PMID 29967776, 2018). "High levels of ROS, produced by cancer cells, induce oxidative stress in CAFs and lead to the production of autophagosomes that fuse with lysosomes, with a consequent mitochondria disruption and Cav-1 degradation." (PMID 29967776, 2018). "Furthermore, Cav-1 downregulation triggers a fibroblast shift toward catabolic metabolism and promotes the mitochondrial activity of adjacent cancer cells." (PMID 29967776, 2018). "Moreover, Zhao studied endometrial stromal-epithelial cell interactions in a non-cancer primary cell culture model and showed that epithelial cell proliferation and migration was enhanced when cultured with conditioned media from CAV1 depleted stromal cells." (PMID 30211120, 2018). "Cav-1 has been described as having a controversial role in cancer development, with pro- and anti-tumorigenic effect depending on the context and the specific cancer type." (PMID 30155439, 2018). "Increased CAV1 expression has also been observed in a series of drug-resistant cancer cells compared with their parental cells such as paclitaxel-resistant A549 cells, vinblastine-resistant SKVLB1 cells, colchicine-resistant HT-29 cells, and adraimycin-resistant MCF-7 cells." (PMID 30333750, 2018). "Caveolin-1 has been detected and reported in leukemic cells, possibly in conjunction with its involvement in cancer, and may reflect tumorigenic changes." (PMID 30246033, 2018).
cancer (continued). "As caveolin-1 was identified to be conjugated with NEDD8, we hypothesized that the neddylation of caveolin-1 determines cancer cell migration." (PMID 29301501, 2018). "Given that CAV1 associates with HER2 and that CAV1 expression in malignancies may be clinically significant for cancer diagnosis, we sought to determine if CAV1 expression is correlated with HER2 density at the cell membrane." (PMID 30510281, 2018). "Moreover, metformin, usually used in the treatment of diabetes, is currently undergoing phase 2/3 clinical trials as adjuvant therapy in several cancer types, for its capacity to restore Cav-1 expression in CAFs." (PMID 29967776, 2018). "Furthermore, in NIH3T3/635 cells after 3D co-culture with cancer cells, a trend of increasing expression was found with Tgfb1 and significantly decreased levels of caveolin-1 mRNA were observed." (PMID 29435153, 2018). "In contrast, when cancer progresses and is treated, CAV1 expression may be upregulated to protect cancer cells from escaping death by speeding aerobic glycolysis, increasing stem cell populations, or overexpressing ATP-binding cassette transporters." (PMID 30333750, 2018). "Furthermore, we showed that MIM-B and caveolin-1 were expressed at higher levels in cancer tissues than in paired adjacent normal tissues and that MIM-B and caveolin-1 expression levels were correlated with HCC clinico-pathologic characteristics." (PMID 29221140, 2017). "Indeed, CAV1 is considered to play a positive role in some cancer studies, but the results of some other studies were exactly the opposite." (PMID 29190968, 2017). "Elucidating the underlying interaction mechanisms between oxidative stress and Cav-1 is helpful for enhancing the preventive effects of antioxidants on cancer, for improving clinical outcomes of antioxidant-related therapeutics in cancer patients, and for developing Cav-1 targeted drugs." (PMID 28546853, 2017). "Furthermore, the prognostic significance of Cav-1 in CAFs remains still debatable in various cancers." (PMID 28828003, 2017). "Through a series of experiments, we found that MIM-B and caveolin-1 expression levels were higher in cancer tissues than in paired adjacent normal tissues and that MIM-B and caveolin-1 expression levels were correlated with HCC clinico-pathologic characteristics." (PMID 29221140, 2017). "In stromal cells, but not in cancer cells, a feedforward mechanism between TGFβ signaling and the loss of CAV1 expression does exist." (PMID 29099748, 2017). "More importantly, emerging evidences have indicated that multiple antioxidants could exert antitumor activities in cancer cells and protective activities in normal cells by modulating the Cav-1 pathway." (PMID 28546853, 2017). "CAV1 is an interesting gene for cancer as it may play different roles in different types of cancer at different stages." (PMID 29190968, 2017). "Thus, we sought to identify stimuli/mechanisms that revert epigenetic CAV1 silencing in cancer cells and evaluate how this affects their metastatic potential." (PMID 29340103, 2017). "Meanwhile, we previously proposed a Cav-1 fluctuation model during cancer development." (PMID 28546853, 2017). "Altogether, these findings indicate that Cav-1 may be a promising oxidative stress-related target for cancer antioxidant prevention." (PMID 28546853, 2017). "Interestingly, Cav-1 was not changed in the Dau rabbit model we employed, despite previous findings that anthracyclines can up-regulate Cav-1 expression in cancer cells." (PMID 28498861, 2017). "Meanwhile, modulating the Cav-1 pathway could significantly affect the oxidative stress status in normal and cancer cells." (PMID 28546853, 2017). "Multiple clinical studies also verified the critical role of Cav-1 for cancer prevention." (PMID 28546853, 2017). "Cordycepin induced apoptosis via CAV1-mediated JNK activation in A549 cancer cells." (PMID 28099944, 2017).
cancer (continued). "Our findings are consistent with a recent report showing that CAV1 upregulation may generate apoptosis in cancer and that the CAV1/JNK/Foxo3a pathway is involved in A549 cell apoptosis after cordycepin treatment." (PMID 28099944, 2017). "Several reports have documented that both MIM-B and caveolin-1 expression levels are significantly altered in various type of cancers and may thus be an independent prognostic factor for different cancers." (PMID 29221140, 2017). "Knowing that STAT3 plays an important role in cancer invasion, and that Cav-1 controls directional cell migration through STAT3, we next asked whether STAT3 activation was required for EF-directed migration of H1650-M3 cells." (PMID 29221162, 2017). "Interestingly, we detected three missence and one silent sequence alterations in Cav-1 from 3 of 50 primary tumors and 1 of 14 cancer cell lines." (PMID 29141593, 2017). "The caveolin-signaling hypothesis proposes that Cav-1 could directly interact with multiple cancer-related signaling molecules including EGFR, Neu, TGF-β, Src, and AKT via the scaffolding domain and negatively modulate their aberrant activations." (PMID 28546853, 2017). "The role of caveolin-1 (CAV1) in cancer is highly controversial." (PMID 28099944, 2017). "We next evaluated CAV1 protein expression in the cancer cells." (PMID 29340103, 2017). "The role of caveolin-1 in different cancer cells is also a controversial subject." (PMID 29221140, 2017). "All these results indicated that elevated ROS production following CAV1 silencing might facilitate cancer formation through activating DNA damage response." (PMID 28546853, 2017). "Based on expression ranges of normal tissues, 30 (30%) and 16 (16%) of 100 primary tumors were classified as abnormally low and high Cav-1 expressors, respectively and 6 (42.9%) and 6 (42.9%) of 14 cancer cell lines were classified as abnormally low and high expressors, respectively." (PMID 29141593, 2017). "Herein, we summarize the available evidence of the roles of Cav-1 and oxidative stress in tumorigenesis and development and shed novel light on designing strategies for cancer prevention or treatment by utilizing the interaction mode between Cav-1 and oxidative stress." (PMID 28546853, 2017). "Moreover, we have previously shown that CAV1 phosphorylation on tyrosine-14 leads to activation of a novel Rab5-Tiam1-Rac1 signalng axis important in migration and invasion of cancer cells." (PMID 29340103, 2017). "For example, it was reported that Cav-1 could sensitize cancer cells to apoptosis in response to death stimuli, and a decrease of Cav-1 expression level was proved to contribute to chemotherapeutic cisplatin and carboplatin resistance." (PMID 28546853, 2017). "Moreover, several reports have documented that caveolin-1 expression is altered in various cancers, such as bladder, ovarian, thyroid follicular, breast, esophageal, lung, colon, cervical, and renal cancer; T cell leukemia; and HCC." (PMID 29221140, 2017). "More importantly, emerging evidence has indicated that multiple antioxidants could exert antitumor activities in cancer cells as well as protective activities in normal cells by modulating the Cav-1 pathway." (PMID 28546853, 2017). "Therefore, it is easy to understand current confusing evidence of Cav-1 in cancer development, and Cav-1 resurrection strategy is promising for preventing normal cells from malignant transformation." (PMID 28546853, 2017). "In addition, Cav-1 has also been reported to be closely connected with the multidrug resistance (MDR) of cancer cells." (PMID 28546853, 2017). "Given these attributes of CAV1, we evaluated the possibility that acute treatments of cancer cells with anti-neoplastic drugs could increase CAV1 expression." (PMID 29340103, 2017).